SPDYE14 (speedy/RINGO cell cycle regulator family member E14)
Synonyms: SPDYE14P
Tractability: No criterion of Open Targets' tractability assessment is met for any kind of drug.
Gene: Protein-coding gene on chromosome 7 (75,307,376 to 75,317,429, forward strand). Ensembl gene ENSG00000286137.
Gene Ontology:
Molecular function: protein kinase binding
Homologues: Orthologues: rat Spdye4 (49% identical), mouse Spdye4a (48% identical), mouse Spdye4b (44% identical). Paralogues in human: SPDYE13 (100% identical), SPDYE15 (100% identical), SPDYE10 (99% identical), SPDYE11 (99% identical), SPDYE17 (99% identical), SPDYE8 (99% identical), SPDYE9 (99% identical), SPDYE12 (99% identical), SPDYE3 (88% identical), SPDYE18 (84% identical), SPDYE16 (83% identical), SPDYE2 (83% identical), and 6 more.